FZD1 (frizzled class receptor 1)
Diseases named in the same sentence as FZD1 in open-access papers (continued):
Sharing a sentence is not in itself a finding about the gene and the disease.
cardiac hypertrophy (2 papers, 2018 to 2022). "In the present study, we identified that FZD1 is an essential mediator of cardiac hypertrophy induced by hypoxic stimuli." (PMID 29423029, 2018). "Together, these data indicated that reduction of FZD1 attenuated hypoxia-induced myocardial growth in vitro rather than cell death, indicating a role of FZD1 in the hypoxia-induced myocardial hypertrophy." (PMID 29423029, 2018). "Silencing FZD1 by siRNA transfection notably repressed the hypoxia-induced myocardial hypertrophy in NRCMs." (PMID 29423029, 2018). "In summary, our study brought a novel therapy of immunization of FZD1 to alleviate cardiac hypertrophy induced by MI." (PMID 29423029, 2018). "We further showed that recombinant mouse FZD1 protein notably attenuated cardiac hypertrophy and improved cardiac function in vivo, which is independent on the effect of myocardial survival." (PMID 29423029, 2018). "Since RFP was able to repress the expression of endogenous myocardial FZD1 in the MI mice, we next interrogated whether such a reduced myocardial FZD1 expression could attenuate the MI-induced cardiac hypertrophy and dysfunction." (PMID 29423029, 2018). "Abundant anti-FZD1 antibodies evoked by RFP bound to the transmembrane receptor FZD1 in the ischemic heart tissue, resulting in an inhibition of the endogenous expression of FZD1, which subsequently repressing the Wnt signalling, and thereby supress the cardiac hypertrophy." (PMID 29423029, 2018). "Given upregulation of FZD1 in hypertrophic hearts under myocardial ischemia, we tested whether an decrease of FZD1 expression prevents cardiac hypertrophy in vitro." (PMID 29423029, 2018). "Furthermore, FZD1 has been independently described as an essential mediator of cardiac hypertrophy." (PMID 35886043, 2022). "Thus, we hypothesized that targeting the FZD1 may open new pharmacological venues for treating cardiac hypertrophy and heart failure after MI to supplement current drugs that target the sympathetic or renin-angiotensin systems." (PMID 29423029, 2018). "Second, to eliminate the possible compensatory or neuroendocrine factors which may influence the expression of FZD1 in the MI-induced cardiac hypertrophy, isolated neonatal rat cardiomyocytes (NRCMs) were stimulated by hypoxia, to mimic MI in an in vitro study." (PMID 29423029, 2018). "Our results also indicated that activation of FZD1/Wnt signaling plays an essential role in the development of cardiac hypotrophy in the post-MI, and that RFP may provide an interesting therapeutic strategy to reduce the endogenous expression of FZD1, thus protects against cardiac hypertrophy." (PMID 29423029, 2018).
glaucoma (2 papers, 2024 to 2025). Increased pressure in the eyeball due to obstruction of the outflow of aqueous humor. "Among them, GADD45B, FZD1, EFNA1, LTBP3, and CST3 have been reported to potentially play a role in the development of both AD and glaucoma." (PMID 40988281, 2025).
glioblastoma (2 papers, 2023 to 2025). The most malignant astrocytic tumor (WHO grade IV). "High expression of FZD1 and FZD8 has been linked to poor overall survival in glioblastoma patients." (PMID 40430278, 2025).
leukemia (2 papers, 2020 to 2022). A malignant (clonal) hematologic disorder, involving hematopoietic stem cells and characterized by the presence of primitive or atypical myeloid or lymphoid cells in the bone marrow and the blood. "Overexpression of FZD1 may cause drug resistance in leukemia cells, whereas silencing FZD1 may reverse multidrug resistance." (PMID 36452482, 2022). "Both Fzd1 and its ligand Wnt3a are important members of the Wnt/Frizzled signaling pathway, decreased expression of which have been implicated in aberrant inflammatory processes and leukemia development." (PMID 33378745, 2020).
liver cancer (2 papers, 2020 to 2023). An epithelial or non-epithelial malignant neoplasm that arises from the liver. "In liver cancer PROM1 was more strongly co-expressed with a larger number of genes, including CFTR, KRT7, ANXA3, TACSTD2, and FZD1." (PMID 31164716, 2020).
myocardial infarction (2 papers, 2019 to 2025). Gross necrosis of the myocardium, as a result of interruption of the blood supply to the area, as in coronary thrombosis. "For example, a mouse model of myocardial infarction showed the dysregulation of expression of WNT2, -4, -7b, -10b and -11 as well as FZD1, -2, -5, -8 and -10, and mice mutants for Dvl1 are more susceptible to infarct rupture after induction of myocardial infarction." (PMID 31382613, 2019).
osteosarcoma (2 papers, 2020 to 2024). A usually aggressive malignant bone-forming mesenchymal neoplasm, predominantly affecting adolescents and young adults. "Inhibition of Sox9 using siRNA has been shown to reduce the expression levels of Wnt1 and Fzd1, resulting in a significant reduction of osteosarcoma cell proliferation." (PMID 38978960, 2024). "Additionally, Sox9 is involved in the regulation of the Wnt1 and Fzd1 signaling pathway, which plays a critical role in osteosarcoma cell proliferation." (PMID 38978960, 2024).
renal cell carcinoma (2 papers, 2021 to 2025). "Lastly, protein expression levels of Wnt3a and Frizzled1 (FZD1) in imatinib-resistant renal cell carcinoma cells were down-regulated by silencing of PDIA6." (PMID 34781823, 2021). "Knockdown of PDIA6 suppressed cell proliferation and DNA damage repair and promoted the apoptosis of imatinib-resistance of renal cell carcinoma through inactivation of activation of Wnt3a-FZD1 signaling." (PMID 34781823, 2021). "The down-regulated p-DNA-PK and Rad51 in A498/R with shPDIA6 transfection was up-regulated by the over-expression of FZD1, indicating that PDIA6 contributed to the imatinib-resistance of renal cell carcinoma through activation of Wnt3a-FZD1 pathway." (PMID 34781823, 2021). "In conclusion, knockdown of PDIA6 sensitized imatinib-resistant renal cell carcinoma cells into imatinib through inactivation of Wnt3a-FZD1 axis." (PMID 34781823, 2021). "Protein expression levels of Wnt3a and FZD1 were down-regulated in A498/R, suggesting that PDIA6 contributed to the activation of Wnt3a-FZD1 pathway in imatinib-resistant renal cell carcinoma." (PMID 34781823, 2021). "In conclusion, knockdown of PDIA6 suppressed cell proliferation and DNA damage repair of imatinib-resistant renal cell carcinoma cell and promoted the cell apoptosis through down-regulation of Wnt3a and FZD1." (PMID 34781823, 2021). "Over-expression of FZD1 attenuated PDIA6 silencing-induced increase in cell apoptosis and decrease in cell proliferation in imatinib-resistant renal cell carcinoma cells." (PMID 34781823, 2021). "Silencing of PDIA6-induced decreases in p-DNA-PK and Rad51 was restored by over-expression of FZD1, suggesting that PDIA6 might contribute to the resistance of renal cell carcinoma to imatinib through activation of Wnt3a/FZD1 pathway." (PMID 34781823, 2021).
schizophrenia (2 papers, 2021 to 2022). A major psychotic disorder characterized by abnormalities in the perception or expression of reality. "The CpG most strongly driving the association with GPF was annotated to FZD1, a gene that has been implicated in schizophrenia and wider neurological processes." (PMID 34118639, 2021).
acute myeloid leukemia (1 paper, 2019). Acute myeloid leukemia (AML) is a group of neoplasms arising from precursor cells committed to the myeloid cell-line differentiation. "In fact, in cells from patients with acute myeloid leukemia (AML), elevated FZD1 expression at diagnosis was associated with more problems in achieving remission, and a tendency to recurrence." (PMID 31921125, 2019).
Alzheimer disease (1 paper, 2020). A progressive, neurodegenerative disease characterized by loss of function and death of nerve cells in several areas of the brain leading to loss of cognitive function such as memory and language. "The genes represented by the age‐DMRs included a few notable members such as Cyp46a1 and Abca7, which are involved in cholesterol metabolism and implicated in Alzheimer's disease, and few members of the WNT signaling and mesenchyme developmental pathways (e.g., Fzd1, Fzd8, Wnt5a, Jak3, Ptk7, Nrp2)." (PMID 32790008, 2020).
breast tumor (1 paper, 2023). "We found that blocking FZD1/2/7-mediated Wnt signaling reduced growth of basal-like tumor models in vivo and also synergized with chemotherapy agent cisplatin in treating breast tumor models." (PMID 37943878, 2023).
dental caries (1 paper, 2012). The decay of a tooth, in which it becomes softened, discolored, and/or porous. "In general, we identified several suggestive loci (P-value ≤ 10E-05) within or near genes with plausible biological roles for dental caries, including RPS6KA2 and PTK2B, involved in p38-depenedent MAPK signaling, and RHOU and FZD1, involved in the Wnt signaling cascade." (PMID 23259602, 2012).
hepatocellular carcinoma (1 paper, 2024). A malignant tumor that arises from hepatocytes. "FZD1 and G6PD are two DR genes that serve as biomarkers for predicting the prognosis of patients with hepatocellular carcinoma." (PMID 38507875, 2024). "These genes, FZD1 and G6PD, demonstrate protumoral functions in hepatocellular carcinoma via various mechanisms." (PMID 38507875, 2024).
inflammatory bowel disease (1 paper, 2022). A spectrum of small and large bowel inflammatory diseases of unknown etiology. "These included elevated methylation levels in CpG islands associated with FZD1 and RUNX3, both of which encode proteins that regulate ovarian folliculogenesis, and also RASAL3, which controls a magnitude of inflammatory responses and has been linked specifically to inflammatory bowel disease." (PMID 34996447, 2022).
Insulin resistance (1 paper, 2021). Increased resistance towards insulin, that is, diminished effectiveness of insulin in reducing blood glucose levels. "Some studies have shown that frizzled class receptor 1 (FZD1) is related to insulin resistance." (PMID 34516309, 2021).
metastatic prostate carcinoma (1 paper, 2022). A carcinoma that arises from the prostate gland and has spread to other anatomic sites. "In primary and metastatic prostate cancer, FZD Wnt receptor genetic mutations are relatively uncommon (<0.6% and 0.23–2.1%, respectively), and although several FZD1-10 mutations have been shown to correlate with copy number alterations, it is not currently known if they alter Wnt receptor activity." (PMID 35204808, 2022).
myocardial ischemia (1 paper, 2018). A disorder of cardiac function caused by insufficient blood flow to the muscle tissue of the heart. "FZD1, a seven-transmembrane receptor abundantly expressed in the heart tissue has been shown to be critically involved in the post cardiac ischemia remodelling." (PMID 29423029, 2018).
osteonecrosis of the femoral head (1 paper, 2019). "Our investigation studied whether aberrant CpG island hypermethylation of the FZD1 gene was present in patients with osteonecrosis of the femoral head (ONFH), which results in Wnt/β-catenin signaling inactivation and subsequent cell dysfunction." (PMID 30808872, 2019).
seminoma (1 paper, 2023). A radiosensitive malignant germ cell tumor found in the testis (especially undescended), and extragonadal sites (anterior mediastinum and pineal gland). "However, we also observed significant associations between high expression of WNT activators (e.g., CTNNB1, FZD1, and FZD7) and poor survival of type II non-seminoma GCT patients, suggesting WNT signaling may be a common driver of adverse outcome in GCT patients across age groups." (PMID 37149691, 2023).
Sepsis (1 paper, 2015). Sepsis is defined as life-threatening organ dysfunction caused by a dysregulated host response to infection. "Therefore, future studies would determine the outcomes after the intervention for maintaining the homeostasis of Fzd1 and Dsh1 in sepsis." (PMID 26218875, 2015).
serous ovarian cancer (1 paper, 2015). "In fact in our previous analysis of high-grade serous ovarian cancer patients, both FZD1 and HGF exhibited significant prognostic properties." (PMID 26100469, 2015).
Shock (1 paper, 2015). The state in which profound and widespread reduction of effective tissue perfusion leads first to reversible, and then if prolonged, to irreversible cellular injury. "We found the lung from rats with endotoxic shock exhibited significant decreases in the levels of Wnt3a, Fzd1, Dsh1, phosphorylated GSK-3β at Ser9, total β-catenin, and nuclear β-catenin when compared with the Control group." (PMID 26218875, 2015).
tendinopathy (1 paper, 2011). "Additionally, tendinopathy tissue showed differential expression of other WNT pathway genes, including increased expression of CTNNB (1.5-fold), WNT5a (2.7-fold), and FZD1 (1.7-fold) and decreased expression of LRP5 (0.59-fold) and FRZB (0.35-fold)." (PMID 21539748, 2011).
teratocarcinoma (1 paper, 2013). A germ cell tumor characterized by the presence of an embryonal carcinoma component and a teratoma component. "Thus far, Gαo and Gαq were shown to be critical during mammalian development, and teratocarcinoma stem cell differentiation in response to oncogenic Fzd1 stimulation." (PMID 24204697, 2013).
tumor (31 papers, 2013 to 2025). "FZD1 is methylated early in prostate cancer initiation, leading to loss of expression, suggesting a potential context-specific tumor suppressive role." (PMID 34604862, 2021). "An FDA-approved antiparasitic drug Niclosamide, suppresses tumor growth and metastasis by targeting FZD1, DVL2, and LRP6 with minimal animal toxicity." (PMID 41516083, 2025). "Transwell cell migration assays demonstrated that FZD1 overexpression promoted tumor cell migration, while the XAV939 β-catenin inhibitor counteracted this metastasis-promoting phenotype." (PMID 40860197, 2025). "It has been reported in many cancer tissues that overexpression of FZD1 can lead to tumor progression and drug resistance." (PMID 36755291, 2023). "FZD1/2/3/4/5/7/8 expression was significantly higher in tumor tissues than in normal brain tissues; however, FZD9 and FZD10 expression was higher in normal tissues." (PMID 36699699, 2022). "It was found that FZD1/2/3/4/5/7/8 was significantly highly expressed in tumor tissues, and the high expression of FZD1/2/5/6/7/8 was significantly positively associated with a poorer prognosis." (PMID 36699699, 2022). "FZD1/2/3/4/5/7/8 was significantly highly expressed in tumor tissues, and the high expression of FZD1/2/5/6/7/8 was significantly positively associated with poorer prognosis." (PMID 36699699, 2022). "Increased expression of Wnt5a and Fzd1 and decreased expression of Lef1 and Camk2a were validated in different tumor samples by quantitative PCR." (PMID 30670683, 2019). "Fzd1, Fzd2, Fzd6, Fzd9, and Fzd10 currently do not have any circRNA molecules associated with regulation of their expression, despite their obvious role in cancer signaling and tumor progression, highlighting the potential for future research." (PMID 34671643, 2021). "Among these 10 genes HDAC1, CASP3, REST, HMG20B, FZD7,GNAI3, FZD1 and EPHB4 had elevated expression in tumor group compared to the normal group, while KCNJ9 and SCRT1 were decreased." (PMID 38629068, 2024). "Collectively, these data indicate that WNT7A/7B ligands and WNT receptors FZD1 and FZD6 mediate the paracrine signalling between pancreatic cancer cells and stellate cells in the tumour." (PMID 38678032, 2024). "Expression of the canonical skeletal muscle WNT agonist Wnt5a (WNT5A), canonical WNT receptor Fzd1 (FZD1), and β‐catenin itself (CTNNB1) was all reduced with C‐26 tumor burden, whereas the negative regulator of β‐catenin, GSK3B, was up‐regulated." (PMID 31930715, 2020). "FZD1 is a Wnt responsive gene in colon-derived tissues which were expressed in CRC, and paracancerous normal mucosa was involved in Wnt signaling within the tumor microenvironment." (PMID 32211321, 2020). "There is evidence that FZD1, a WNT receptor dedicated to the β-catenin pathway, mediates the expression of the multidrug-resistance-protein 1 (MDR1) efflux-transporter that confers drug resistance to tumor cells." (PMID 29058015, 2018). "None of the new chimeric mice showed accelerated tumorigenesis or higher incidence of tumors, yet 3 of 4 tumors harboring CDK14 or CDK14/CDK6/FZD1 were easily propagated, strongly suggesting that overexpression of CDK6 and CDK14 are important for ectopic tumor growth and metastasis." (PMID 25162504, 2014). "Niclosamide promoted LRP5/6 degradation, Wnt receptor Fzd1 endocytosis, downregulation of Dvl2 proteins, and inhibition of Wnt3A-stimulated β-catenin stabilization and TCF/LEF reporter activity as well as enhanced cytotoxicity in all the patient derived tumor spheres." (PMID 34068065, 2021). "In BCPAP cells treated for 72 h, genes from the canonical Wnt pathway (FZD1, DVL1, AKT2, CTNNB1, LEF1, MYC) and the non-canonical Wnt pathway (RHOA, related to cytoskeletal dynamics and increased migration and invasion) were upregulated, suggesting pro-tumor behavior." (PMID 39125748, 2024).